CBS (cystathionine beta-synthase)
Diseases named in the same sentence as CBS in open-access papers (continued):
Sharing a sentence is not in itself a finding about the gene and the disease.
ovarian carcinoma (continued). "We observed that the expression of CBS in cancer cells induces an affinity for lipids and ovarian cancer cells effectively migrated and invaded towards a lipid gradient." (PMID 26452259, 2015). "Absence of CBS abrogated the uptake of PDDA in siCBS-A2780 cells, indicating a role of CBS in lipid uptake in ovarian cancer cells." (PMID 26452259, 2015). "Our previous study identified roles of CBS in ovarian cancer maintenance and drug resistance, while the aberrant expression of SREBPs have been implicated in many forms of cancer." (PMID 26452259, 2015). "We show a role of CBS and SREBPs in cell proliferation, migration and invasion of ovarian cancer cells." (PMID 26452259, 2015). "To understand the role of CBS in human ovarian cancer, we assessed the expression level of CBS in primary ovarian cancer specimens and its relationship to surgical-pathologic factors." (PMID 24236104, 2013). "Given the remarkable effects of CBS in vitro, we next tested the effect of CBS knockdown in an orthotopic mouse model of ovarian cancer (A2780/CP-20)." (PMID 24236104, 2013). "A significant decrease in proliferation was observed in all ovarian cancer cell lines studied upon CBS knockdown by (3H)-thymidine incorporation." (PMID 24236104, 2013). "Using patient tissue microarray (TMA), in vitro and in vivo studies we report a role of of cystathionine-beta-synthase (CBS), a sulfur metabolism enzyme in ovarian carcinoma." (PMID 24236104, 2013). "The outcome of these experiments signifies the potential of CBS as a therapeutic target in ovarian cancer, the inhibition of which would lead to disturbance in redox homeostasis and mitochondrial functioning." (PMID 24236104, 2013). "Our studies, however, show that ovarian cancer cells utilize CBS to support mitochondrial ATP production and at the same time protects against damage from leaky ETC by maintaining redox homeostasis." (PMID 24236104, 2013). "Having confirmed that CBS is expressed both in cell lines, and in primary ovarian cancers we next sought to examine the functional significance of CBS." (PMID 24236104, 2013). "The present investigation highlights CBS as a potential therapeutic target in relapsed and platinum resistant ovarian cancer." (PMID 24236104, 2013). "To further confirm the effects of CBS silencing on ovarian cancer cell viability, we used a specific chemical inhibitor of CBS, Aminoxyacetic Acid (AOAA)." (PMID 24236104, 2013). "Silencing CBS significantly decreased total cellular glutathione (GSH+GSSG) levels in ovarian cancer cells dramatically compared to the control cells." (PMID 24236104, 2013). "Silencing CBS significantly inhibits ovarian cancer cell proliferation, metastatic nodule formation and sensitizes them to cisplatin both in vitro and in pre-clinical orthotopic mouse models in vivo." (PMID 24236104, 2013). "In addition, CBS has been proposed to promote ovarian cancer progression, tumor growth, and drug resistance, while CSE has been associated with breast cancer metastasis promotion." (PMID 38933705, 2024). "Inhibition of CBS can improve ovarian cancer treatment as well." (PMID 37483514, 2023). "Similarly, suppressing H2S production via silencing the CBS gene reduced angiogenesis in colon and ovarian cancer." (PMID 37627515, 2023). "The A2780 ovarian cancer cell line showed both cytoplasmic and mitochondrial CBS expression." (PMID 35366284, 2021). "Additionally, in ovarian cancer cell lines, CBS expression maintains mitofusin-2 expression, with CBS knockdown lowering mitofusin-2 expression, causing mitochondrial fragmentation with a fused spherical morphology and increased unbranched mitochondria." (PMID 34829691, 2021). "The expression of CBS is increased in ovarian cancer cell line A2780." (PMID 34335475, 2021). "CBS and H2S may be involved in regulating proliferation and bioenergetics in breast cancer, ovarian cancer, and colorectal cancer, and high levels of CBS, CSE, and 3MST expression were observed in lung cancer." (PMID 34208749, 2021).
ovarian carcinoma (continued). "Recent studies have shown that CBS promotes the growth of colon and ovarian cancer in preclinical models, and CBS blockers have the potential as adjuvants in the treatment of breast cancer to reduce the ability of cancer cells to resist oxidative stress induced by many chemotherapeutic drugs." (PMID 34778244, 2021). "However, CBS has been also reported as having oncogenic properties in breast, as well as in colon and ovarian cancers." (PMID 32078659, 2020). "Consistent with our data, another study demonstrated that silencing of CBS or SREBPs eliminated cell migration and invasion in ovarian cancer, whereas ectopic expression of SREBPs rescues the phenotypic effect of CBS silencing by restoring cell migration and invasion." (PMID 31299935, 2019). "Ovarian cancer cells depleted of CBS showed enhanced ROS production." (PMID 30050925, 2018). "To further investigate whether CBS-regulated SREBPs expression is responsible for proliferation, migration and invasion of ovarian cancer cells, we transiently silenced ovarian cancer cell lines with siRNA for SREBP1 and SREBP2." (PMID 26452259, 2015). "Our TLC/GC-FID approach revealed CBS regulates the expression of most FAs in ovarian cancer." (PMID 26452259, 2015). "Indeed our previous work showed for the first time the roles of CBS and thereby H2S in chemoresistance in ovarian cancer." (PMID 26452259, 2015). "We further attempted to realize whether restoring SREBPs in a CBS knockdown milieu could rescue the migratory and invasive phenotype of ovarian cancer cells." (PMID 26452259, 2015). "Hence we propose a therapeutic opportunity in ovarian cancer by selective targeting of CBS that orchestrates fueling of cancer cells by aberrant lipid metabolism." (PMID 26452259, 2015). "Furthermore, CBS also regulates bioenergetics of ovarian cancer cells by regulating mitochondrial ROS production, oxygen consumption and ATP generation." (PMID 24236104, 2013). "Moreover, selenium-containing chrysin, as a compound with anticancer and antioxidant effects, shows an antitumor effect in many ovarian cancer cell lines, and its inhibitory effect is achieved by inhibiting the expression of CBS and promoting the transformation of GSH." (PMID 34335475, 2021). "We also examined whether CBS affects the cellular invasion in ovarian cancer." (PMID 26452259, 2015). "Taken together, CBS could be an excellent point of therapeutic intervention in ovarian cancer." (PMID 24236104, 2013). "The expression of CBS is already identifiable in most of the early stages (FIGO Stage I and II) of the ovarian cancers studied." (PMID 35684331, 2022). "Previous studies have shown strong levels of CBS expression in the FIGO stages (I and II) of ovarian cancer." (PMID 35684331, 2022). "The clinical relevance of CBS and MFN2 expression in ovarian cancer was examined in the clinically annotated mRNA data from The Cancer Genome Atlas (Gene Expression Omnibus) databases." (PMID 35366284, 2021). "In ovarian cancer cell lines, depletion of the enzyme that catalyzes the metabolic step prior to CTH, cystathionine beta synthase (CBS), induces reactive oxygen species (ROS) accumulation leading to reduced mitochondrial respiration and ATP synthesis." (PMID 27713570, 2016). "Here, we identify a novel role of cystathionine beta-synthase (CBS), a sulphur amino acid metabolizing enzyme highly expressed in several ovarian cancer cell lines, in driving deregulated lipid metabolism in OC." (PMID 26452259, 2015). "However, forced overexpression of SREBP1a, SREBP1c and SREBP2 in CBS silenced cells could partially restore migratory and invasive behavior of all the three ovarian cancer cell lines tested, establishing a direct link between CBS and SREBPs in cellular motility in ovarian cancer." (PMID 26452259, 2015).
ovarian carcinoma (continued). "Previous studies have indicated that APOC1 serves as a prognostic marker for cervical cancer, ovarian cancer, and liver cancer, and it promotes glioblastoma tumorigenesis by inhibiting ferroptosis regulated by the KEAP1/NRF2 and CBS." (PMID 39877420, 2024). "Also, Nrf2 enhances the expression of CBS through antioxidant response element (ARE) and high expression of CBS mitigates ferroptosis induced by erastin (xCT‐specific inhibitors) in ovarian cancer by regulating S‐adenosyl homocysteine, homocysteine, and CTH." (PMID 36929586, 2023). "High expression of CBS and MFN2 has a poor prognosis for ovarian cancer." (PMID 36929586, 2023). "Another study by a group used quantitative RT-PCR and immunoblotting to compare the expression of CBS mRNA and protein levels in different ovarian cancer cell lines with a non-malignant superficial ovarian cell line as a control (OSE)." (PMID 35684331, 2022). "High CBS and CSE expression confer a poor prognosis in ovarian cancer." (PMID 35366284, 2021). "Antioxidant glutathione, but not H2S, fully rescued viability of CBS-depleted cells, suggesting that the effect of CBS in ovarian cancer cells is mediated through regulation of ROS production by glutathione." (PMID 30050925, 2018). "CBS silencing resulted in significant reduction in the expression of SREBP at the protein levels as well, suggesting a regulatory effect of CBS in lipid metabolism pathway in ovarian cancer." (PMID 26452259, 2015). "Absence of CBS prevented the cancer cells to migrate or invade in a LPA gradient, indicating a role of CBS promoting migration and invasion of ovarian cancer cells towards lipid rich environment." (PMID 26452259, 2015). "Our results, however, indicate that CBS supports ATP synthesis under resting conditions in ovarian cancer cells that could be mediated through H2S or GSH and clearly implicates a novel role for CBS in cancer cells rather than CSE which is marginally expressed." (PMID 24236104, 2013).
breast cancer (40 papers, 2014 to 2025). A primary or metastatic malignant neoplasm involving the breast. "The accumulation of cystathionine in breast cancer tissue is said to be associated with the overexpression of CBS." (PMID 32041330, 2020). "Soon afterwards, Gallegos-Arreola and colleagues reported that the 844ins68 polymorphism in the CBS gene contributes significantly to breast cancer susceptibility in Mexican population." (PMID 27808252, 2016). "In summary, we have shown a significant association among MS, MTRR, SHMT, CBS polymorphisms, elevated plasma Hcy levels and increased risk of breast cancer." (PMID 24559276, 2014). "Cystathionine and CBS are both found in higher concentration in breast cancer tumor tissue compared to healthy breast tissue, and an analysis from the Women's Health Study found a positive association between circulating cysteine and breast cancer risk." (PMID 35366005, 2022). "The pro-cancer effect of CBS in human breast cancer has been further consolidated by a recently reported association between the 844ins68 polymorphism in the CBS gene and the occurrence of breast cancer." (PMID 32041330, 2020). "Therefore, we investigated whether the genetic variants of the SHMT, MS, MTRR and CBS gene can affect plasma Hcy levels and are associated with breast cancer risk." (PMID 24559276, 2014). "CBS involvement (indirect via the produced H2S) was also described as one responsible for the protective features for breast cancer against the macrophages." (PMID 38397425, 2024). "Several studies have demonstrated that overproduction of H2S occurs in breast cancer (BC) and correlated the upregulation of H2S synthesizing-enzymes, namely cystathionine-β-synthase (CBS) and cystathionine-γ-lyase (CSE), with poor clinical prognosis." (PMID 38627665, 2024). "It is worth mentioning that, recently, miR-548 and miR-193 have been found by our research group to simultaneously target the three synthesizing enzymes in breast cancer: CBS, CSE and 3MST." (PMID 38250807, 2024). "The elevated expression of CBS is responsible for inducing tumor growth in other gynecological cancers, including ovarian and breast cancer." (PMID 36984849, 2023). "With respect to breast cancer, the first report was published by Sen and colleagues in 2015, demonstrating that CBS is upregulated in human breast cancer cell lines, H2S is produced in excess, and it serves as a tumor cell-supporting mediator." (PMID 36978895, 2023). "CBS is dysregulated in different types of cancer, which is upregulated in kidney, colorectal, ovarian, lung, and breast cancer but downregulated in glioma and liver cancer." (PMID 36733406, 2023). "In the breast cancer tissues where CBS and CSE are highly expressed, CBS and CSE play important roles in sulfur metabolism and tumorigenesis." (PMID 37107243, 2023). "CBS has been reported to be expressed at a high level in certain cancers, including kidney, colorectal, lung, and breast cancers, but at a low level in liver cancer and glioma." (PMID 37283791, 2023). "The pro-ferroptotic effect of CSE depletion aligns with a recent study reporting that depletion of cystathionine β-synthase (CBS), another enzyme capable of supporting persulfide biosynthesis, promotes ferroptosis in breast cancer cells." (PMID 36109647, 2023). "The current work, utilizing a murine breast cancer cell line, focused on the expression of all major H2S-generating and H2S-metabolizing enzymes and tested the effect of pharmacological inhibition of CBS/CSE vs. 3-MST on a variety of functional parameters." (PMID 36978895, 2023). "Disruption of CBS inhibits both hypoxic response and tumor angiogenesis in basal-like breast cancer cell-derived xenograft tumors, which have larger intratumoral necrotic areas." (PMID 36741694, 2022). "Anti-proliferative effect and diminished malignant transformation are observed after CBS silencing in basal-like breast cancer cells." (PMID 36741694, 2022).
breast cancer (continued). "CBS, as previously indicated, is found at the cancer cell membrane in breast cancer, where CBS-derived H2S protects the cancer cells from activated macrophage-generated ROS." (PMID 35684331, 2022). "Among these prognosis-associated genes, four genes, AHCY, CBS, DNMT3A, and MTAP (p-value < 0.05), were common markers of poor prognosis for neuroblastoma and breast cancer." (PMID 36361596, 2022). "CBS mRNA and protein levels were also higher in breast cancer cell lines compared to benign mamillary epithelial cells, with the cancer cells lines producing 2 to 4-fold more H2S and 64-fold more cystathionine than the benign cells." (PMID 35366284, 2021). "CBS expression was significantly increased in breast cancer, and increased further with higher breast cancer stages, with the highest expression in metastatic disease." (PMID 35366284, 2021). "As previously discussed, in breast cancer CBS localizes to the cancer cell membrane, where CBS-derived H2S protects the cancer cells from activated macrophage-generated ROS." (PMID 35366284, 2021). "Cell fractionation experiments revealed that CBS localized to the breast cancer cell membrane, demonstrating that CBS conferred resistance to macrophage-generated ROS by plasma membrane H2S synthesis." (PMID 35366284, 2021). "A tissue microarray was employed to analyze CBS expression in 60 breast cancer cases compared to adjacent benign tissue." (PMID 35366284, 2021). "Usually CBS cannot be detected in normal breast tissues, but it is strongly overexpressed in breast cancer cells." (PMID 32365821, 2020). "It is also worth noting that the impact of CBS on tumor growth and progression is context-dependent, with CBS functioning as an oncogene in colon, ovarian and breast cancer but as a tumor suppressor in liver cancer." (PMID 32770044, 2020). "In breast cancer, CBS-derived H2S might play a role in the protection of breast cancer cells against activated macrophages." (PMID 37483514, 2023). "CBS is also highly expressed in basal‐like breast cancer (BLBC)." (PMID 36929586, 2023). "Importantly, in murine xenograft models, breast cancer cell growth was markedly slower in CBS-silenced cells than the growth of wild-type cells." (PMID 36978895, 2023). "By the analysis of transcriptomic data of more than 1500 cancer cell lines and patient samples, we show that the high expression of four genes from the methionine metabolism pathway (AHCY, CBS, DNMT3A, and MTAP) is associated with poor prognosis for breast cancer and neuroblastoma patients." (PMID 36361596, 2022). "Additionally, following three weeks growth in murine xenograft models, CBS siRNA knockdown in breast cancer cells resulted in lower tumor volumes compared to cells without knockdown (8 mm2 vs. 125 mm2)." (PMID 35366284, 2021). "In addition, cristae formation was reduced in CBS-silenced breast cancer cells with vacuolated mitochondria, and there was evidence for mitochondrial permeability transition pore opening." (PMID 32365821, 2020). "They suggested that CBS-derived H2S might have protected breast cancer cells from the attack of microphage instead of directly promoting cell growth." (PMID 32041330, 2020). "Similarly, reduced glutathione abundance was observed in breast cancer cells upon CBS silencing and was accompanied by decreased Nrf2 expression." (PMID 30050925, 2018). "For instance, CBS-derived H2S has been shown to exert immunosuppressive effects by protecting breast cancer (BC) cells from activated macrophage-generated reactive oxygen species (ROS) in macrophage-BC cell cocultures." (PMID 39643979, 2024). "Moreover, patient-derived basal-like breast cancer tumors exhibited elevated expression of CBS." (PMID 36741694, 2022). "Interestingly, cystathionine is also highly enriched in breast cancer due to high CBS expression." (PMID 35366284, 2021). "Thus, CBS may also promote breast cancer via the production of this cancer-protective oncometabolite." (PMID 35366284, 2021).